NOX5 (NADPH oxidase 5)
Diseases named in the same sentence as NOX5 in open-access papers (continued):
Sharing a sentence is not in itself a finding about the gene and the disease.
diabetic foot ulcer (1 paper, 2020). "In summary, inhibition of circulating exosomal miR-15a-3p accelerated diabetic wound repair by activating NOX5, providing a novel therapeutic target for diabetic foot ulcer therapy." (PMID 32439831, 2020).
glioblastoma (1 paper, 2024). The most malignant astrocytic tumor (WHO grade IV). "While NOX5 is primarily expressed in tissues including the spleen and testis, the expression of NOX5 in the brain has been observed in cell types such as oligodendrocytes and glioblastoma (GBM), a type of cancer that starts in astrocytes." (PMID 39596364, 2024).
histiocytic lymphoma (1 paper, 2020). "In histiocytic lymphoma U937 cells, NDRG2 could modulate NOX5-ROS-PKR pathway-regulated Bak-to-Mcl-1 ratio to increase the sensitivity to cisplatin." (PMID 32345304, 2020).
hypospadias (1 paper, 2022). Hypospadias is the displacement of the urethral meatus on the ventrum of the penis. "We also identified Rho kinase activation, Nox5-induced ROS generation, redox-regulated signalling, and epigenetic changes in VSMCs as important molecular mechanisms underlying vascular alterations in hypospadias." (PMID 35567552, 2022). "Of the many Nox isoforms identified in VSMCs,48 we found increased expression of Nox5 and hyperoxidation of redox-sensitive proteins (peroxiredoxin) in hypospadias." (PMID 35567552, 2022).
imperforate anus (1 paper, 2021). A congenital birth defect characterized by the absence of a normal anal opening. "The ganglionic segments in HSCR patients and imperforate anus patients had a similar expression level of NOX5." (PMID 33784990, 2021).
ischaemic stroke (1 paper, 2013). "A notable limitation to pre-clinical studies in the rat and mouse is the absence of Nox5 in their respective genomes and studies investigating the role of Nox5 after ischaemic stroke in different species are lacking." (PMID 24961415, 2013).
leukemia (1 paper, 2019). A malignant (clonal) hematologic disorder, involving hematopoietic stem cells and characterized by the presence of primitive or atypical myeloid or lymphoid cells in the bone marrow and the blood. "Human monocytes and macrophages were also found to express Nox5; however, studies were performed mainly in human leukemia cell line cells (leukemia cell line)." (PMID 30334629, 2019).
lung adenocarcinoma (1 paper, 2019). A carcinoma that arises from the lung and is characterized by the presence of malignant glandular epithelial cells. "Although the total expression levels of NOX5 are low in individual patients, the increases or decreases vary from −192% to 426%, thereby suggesting that mutations and alterations in signal transduction pathways in lung adenocarcinoma markedly affect NOX5 regulation." (PMID 29478325, 2019).
malaria (1 paper, 2013). Malaria is a serious and sometimes fatal disease caused by a parasite that commonly infects a certain type of mosquito which feeds on humans. "The process of nitration is clearly an essential step in the destruction of malaria parasites, evidenced by the significant increase in parasite survival upon silencing either HPx2 or NOX5." (PMID 24039583, 2013).
metastatic melanoma (1 paper, 2023). A melanoma that has spread from its primary site to another anatomic site. "In melanocytic lineages, Nox1, Nox4, and Nox5 are expressed; Nox4 expression is significantly higher in a subset of metastatic melanoma tumors, while in primary and metastatic melanoma tissues, Nox1 is not differentially expressed." (PMID 37189846, 2023).
non-small cell lung carcinoma (1 paper, 2024). A group of at least three distinct histological types of lung cancer, including non-small cell squamous cell carcinoma, adenocarcinoma, and large cell carcinoma. "Additionally, a recent study found that PD treatment synergistically enhances cisplatin’s antitumor effects in non-small cell lung cancer (NSCLC) cells by increasing ROS production through NADPH oxidase 5 (NOX5) activation." (PMID 39852136, 2024).
pancreatic adenocarcinoma (1 paper, 2023). "To assess whether these NOX5:actin effects occurred with endogenously expressed NOX5, we employed PSN-1 cells, a human pancreatic adenocarcinoma cell line in which NOX5 is among the highest over-expressed genes." (PMID 36776559, 2023).
parasite infection (1 paper, 2022). "To investigate the molecular mechanism underlying hemocyte nitration induced by CSPmut parasite infection, we silenced the upregulated antioxidant genes (NOX5, DUOX, DBLOX, and HPX2) and determined the effect on hemocyte nitration." (PMID 35680915, 2022).
prostate tumor (1 paper, 2016). "Together these findings support the notion that Nox5 activation and subsequent ROS production contribute to prostate tumor cell malignancy." (PMID 25559363, 2016).
Sepsis (1 paper, 2017). Sepsis is defined as life-threatening organ dysfunction caused by a dysregulated host response to infection. "The different expression of miRNA might potentially be used to discriminate septic AKI from sepsis-non AKI and they were correlated with the regulation of mitochondrial oxidative stress and dysfunction, including PGC-1α, SIRT1, mTOR, OXSR1 and NOX5." (PMID 28296904, 2017).
type 1 diabetes (1 paper, 2024). "Considering the view that both NOX4 and NOX5 appear to play roles in DKD, we examined the pathogenic role of NOX5 in the presence or absence of NOX4 expression using endothelial cell (EC)-specific NOX5 transgenic mice in a streptozotocin (STZ)-induced insulin-deficient type 1 diabetes model." (PMID 38671844, 2024).
cancer (35 papers, 2013 to 2025). A tumor composed of atypical neoplastic, often pleomorphic cells that invade other tissues. "In the present research, we investigated the interaction between NOX5‐positive cancer cells and CAFs, and examined the underlying mechanisms." (PMID 34459125, 2021). "NOX5 has also been associated with sensitivity of cancer cells to chemotherapeutic drugs, such as cisplatin." (PMID 30801870, 2019). "In skin, breast and lung cancer cells, cisplatin treatment increased expression of NOX5, with an associated increase in ROS‐mediated cancer cell death; responses that seem to be dose dependent." (PMID 30801870, 2019). "NOX5‐derived ROS have been implicated in a number of pathologies, especially cardiovascular disease, renal disease and cancer." (PMID 30801870, 2019). "Interestingly, NOX5 knockdown has been associated with lower phosphorylation levels of AKT in cancer favoring cell survival." (PMID 37566320, 2023). "The exact pathophysiological significance of NOX5 remains unclear, but it seems to be important in the physiological regulation of sperm motility, vascular contraction and lymphocyte differentiation, and NOX5 hyperactivation has been implicated in cardiovascular disease, kidney injury and cancer." (PMID 30801870, 2019). "In physiological conditions, NOX5‐induced ROS generation seems to be important in the regulation of sperm motility, smooth muscle contraction and lymphocyte function, and in pathological conditions it has been implicated in cardiovascular disease, kidney disease and cancer." (PMID 30801870, 2019). "For this reason, the increase in NOX5 activity is related to the progression of various pathologies such as vascular and renal diseases and cancer." (PMID 36905456, 2023). "For example, the increase in NOX5 activity is related to the development of various oxidative stress-related pathologies such as cancer, cardiovascular, and renal diseases." (PMID 36905456, 2023). "Supporting our findings others have demonstrated that NOX5 regulates c-Src through oxidation in human cancer cell lines." (PMID 34320175, 2022). "Previous studies have demonstrated that NOX5 is involved in various pathological conditions, including cancer, cardiovascular and atherosclerotic diseases." (PMID 33784990, 2021). "In other study, DHTS has been shown to inhibit cancer stem cells (CSCs) in TNBC cell line i.e. MDA-MB-231 by activation of NOX5 mediated ROS/Stat3/IL-6 pathway." (PMID 34319041, 2021). "The SRC proto-oncogene has been demonstrated to activate NADPH oxidases NOX1-, NOX3-, NOX4-, and NOX5-induced O2•− production in cancer models and to increase mutant SOD1 aggregate formation in ALS." (PMID 29478325, 2019). "NOX5 mRNA expression suggests minimal average changes showing an 8.4% (SD 256.9) decrease in primary cancer and a 26.3% (SD 317.4) increase in metastasis." (PMID 29478325, 2019). "Taken together, NOX5 has been suggested as a potential target of cancer cell sensitivity to chemotherapies, such as cisplatin." (PMID 30801870, 2019). "In humans, high expression of Nox5 which is accompanied by excess ROS has been reported in both cancer and cardiovascular disease." (PMID 27486403, 2016). "Benign epithelium as well as cancer cells displayed Nox5 immunoreactivity of varying intensities in different cases with varying tumor/benign ratios." (PMID 25559363, 2016). "Given the absence of Nox5 from the genomes of rats and mice, the importance of Nox5 to the development of cardiovascular diseases, cancer and other diseases is, by comparison, poorly understood." (PMID 27486403, 2016). "Nonetheless, there is a growing consensus that the level of NOX5 is an important factor in certain cancers, such as prostate cancer, esophageal adenocarcinoma, and melanomas." (PMID 26513170, 2015). "NOX5 expression has been observed in some cancer cells, but it is rarely detected in normal cells, except those of reproductive and vascular systems." (PMID 26513170, 2015).
cancer (continued). "The NADPH oxidase, NOX5, is known to stimulate cell proliferation in some cancers by generating reactive oxygen species (ROS)." (PMID 26513170, 2015). "Surprisingly, our data reveal that RV treatment selectively increases Nox5 expression in both A549 and H460 cells, suggesting that RV-induced ROS generation in cancer cells is likely attributable to increased Nox5 expression." (PMID 23533664, 2013). "To better understand how RV induces ROS generation in cancer cells, we investigated if RV treatment has any impact on the expression of Nox1, Nox2, Nox3, Nox4 and Nox5 in NSCLC cells." (PMID 23533664, 2013). "This suggests that Nox5 may protect against cancer by reducing fibronectin, and that tumor tendency may be lower in eNOX5ki/ki mice." (PMID 35798762, 2022). "Other interesting candidates were NOX5, whose activation was demonstrated to inhibit cancer stem cell formation through ROS generation, and SALL3, which was reported to directly inhibit DNMT3A activity and consequently cause DNA hypomethylation and activation of tumor suppressor genes." (PMID 34439480, 2021). "Therefore, it is potential that NOX5 has a dual effect on cancers, which needs to be verified with further research." (PMID 33889544, 2021). "NOX5 has also been demonstrated in many non‐immune cells and tissues, including placenta, bone marrow, uterus, stomach, skeletal muscle, cancer cells and hepatocytes and in cells of the cardiovascular system, such as cardiomyocytes, endothelial and vascular smooth muscle cells." (PMID 30801870, 2019). "Nox1, Nox4, and Nox5 have been identified in various types of cancers." (PMID 30334629, 2019). "The Nox5 gene is expressed in a variety of fetal tissues and in adult testes, spleen, lymph nodes, pancreas, placenta, bone marrow, uterus, kidney, stomach, and cancer cells." (PMID 30334629, 2019). "Increased expression of Nox5 in cancer and cardiovascular disease suggest an important role in pathophysiology, but in the absence of appropriate tools this hypothesis has not advanced beyond speculation." (PMID 27486403, 2016). "The expression of Nox5 is also increased in cancers and may contribute to enhanced cellular proliferation and resistance to apoptosis." (PMID 24992705, 2014). "Nox5 expression is also known to be upregulated in development, cancer, and cardiovascular diseases, but whether it influences the pathogenesis of disease is not year clear." (PMID 24992705, 2014). "Higher levels of Nox5 expression have been observed in cancers and cardiovascular disease suggesting it may have important roles in the pathogenesis of human disease." (PMID 24992705, 2014). "In human cells, Nox5 has been ascribed numerous roles including the development and capacitation of sperm, smooth muscle proliferation and migration, endothelial cell proliferation and angiogenesis and cancer cell proliferation and resistance to apoptosis." (PMID 24992705, 2014). "More importantly, our studies demonstrate for the first time that RV selectively increases Nox5 expression in NSCLC cells, suggesting that RV may induce ROS generation in cancer cells via upregulating Nox5 expression." (PMID 23533664, 2013). "Together, these data suggest that RV may induce ROS generation in cancer cells through up-regulating Nox5 expression." (PMID 23533664, 2013). "Notably, most NOX5 studies have focused on NOX5-S as a mediator of cancer cell proliferation." (PMID 26513170, 2015). "Mitochondria and NOXs family, including NOX1, NOX2, NOX3, NOX4, NOX5, DUOX1, and DUOX2, are two important sources of ROS production in cancer cells." (PMID 35418176, 2022). "Mitochondria and NADPH oxidases of the Nox family including NOX1, NOX2, NOX3, NOX4, NOX5, DUOX1 and DUOX2, are two important sources of ROS production in cancer cells." (PMID 30755243, 2019). "The data demonstrate stable and low mRNA expression of NOX1, NOX3, NOX4, and NOX5, whereas the expression of NOX2 is markedly higher and variable in different forms of cancer." (PMID 29478325, 2019).
cancer (continued). "Other investigators detected NOX5 mRNA in benign prostate cancer cells (RWPE1) and cancer cell lines (LNCaP, VCaP, DU145, and PC-3), with the highest levels being observed in LNCaP and PC-3 cells." (PMID 29065504, 2017). "The role of NOX5 is less understood than those of NOX1, 2, and 4, but it is also reported to play a significant function in cancer." (PMID 28626501, 2017). "Therefore, future studies of cancers, in particular NSCLC, in Nox5 KI mice expressing Nox5 in endothelial cells and other cell types is warranted." (PMID 35798762, 2022). "Many types of cultured cancer cell lines and human tumors at early and late stages of tumorigenesis express higher levels of NOX1, NOX2, NOX4, and NOX5 or their regulatory components compared with normal controls, suggesting a pivotal role either in cancer development or in progression." (PMID 34204425, 2021). "An interesting study, suggesting that cancer stem cells are known to mediate metastasis and recurrence and are therefore a promising therapeutic target, is focused on the CSC inhibitory effect of dihydrotanshinone (DHTS) that involves NOX5 activation." (PMID 34204425, 2021). "Altered expression and activity of Nox5 has been reported in cardiovascular diseases and cancers but the absence of Nox5 in rodents has precluded a greater understanding of its physiological and pathophysiological roles." (PMID 24992705, 2014). "In addition, it has been reported that protein expression levels of NOX-5 are not significantly different between cancer and benign tissues." (PMID 29065504, 2017). "To test the effect of NOX2 and NOX5 on mammosphere formation, we performed siRNA-inducing silencing of NOX2 and NOX5 expression, which did not reduce the mammosphere formation in MDA-MB-231 cancer cells." (PMID 31019654, 2019).
tumor (23 papers, 2016 to 2025). "Enhancing the NOX5 activity on cell membrane cause subsequently concentrates the local ROS oxidization and activates oncoprotein-Src to promote malignancy of tumor cells." (PMID 34868391, 2021). "For example, NOX4 senses oxygen, produces ROS and is associated with tumor growth, and NOX5 and NCF2 produce superoxide." (PMID 26590118, 2016). "In colon cancer, NOX5 participates in the regulation of integrin-linked kinase signaling pathways, which are involved in cell adhesion and movement, correlating with the motility of tumor cells." (PMID 39696702, 2024). "Nox5 has been implicated in several malignancies, however its role in tumor cell biology remains unclear." (PMID 25559363, 2016). "NOX2, NOX4, and NOX5 mRNA levels increased with tumor progression stages, while NOX1 and DUOX1 expression decreased in more advanced stages." (PMID 38542437, 2024). "NADPH oxidase 5 (NOX5) is overexpressed in the tumour tissues of ESCC patients, and this overexpression has negative association with the development and prognosis of ESCC." (PMID 37927475, 2023). "In fact, it has been demonstrated in different tumor cell lines, depending on its levels, NOX5 promotes proliferation when it is slightly overexpressed and apoptosis above certain threshold levels." (PMID 36358519, 2022). "The NOX family, which includes NOX1, NOX2, NOX3, NOX4, and NOX5 subtypes, is a key mediator of cyclic hypoxia-mediated ROS production and tumor progression." (PMID 36278207, 2022). "As for another gene, NOX5 showed the role of tumor suppressor genes in STS, which was lower expressed in tumors and beneficial for prognosis." (PMID 33889544, 2021). "Our findings together indicate that NOX5 serves as the driving oncoprotein to provide a niche that is beneficial for tumor malignant progression." (PMID 34459125, 2021). "Our previous study demonstrated that the NADPH oxidase 5 (NOX5) level in ESCC tissue samples was tightly related to tumor malignant progression and the shorter survival of ESCC patients." (PMID 34459125, 2021). "In this study, we intended to evaluate the expression of all members of the NOXs family in ESCC and establish the correlation between NOX5 expression and tumor malignancy." (PMID 32792487, 2020). "Strong expression of NOX5 was positively correlated with advanced-stage, higher grade tumor status and higher grade lymph node status." (PMID 32792487, 2020). "Regarding the pathological roles of NOX5, several reports have shown that downregulation of NOX5 expression inhibits cell proliferation and tumor growth and induces apoptosis in PC cells." (PMID 29065504, 2017). "Increased mRNA expression of NOX5 has been detected in cell lines and tumor tissues of various malignancies, including melanoma and breast cancer, but not in colorectal, hepatic, and ovarian cancer and Ewing’s sarcoma." (PMID 29065504, 2017). "In addition, the activity of NOX5 is also responsible for the increased tumor cell invasion of human prostate, colon, and breast tumor cell lines." (PMID 36905456, 2023). "Furthermore, tumor cells are subject to FFA-induced oxidative stress via NADPH oxidase 5, which aids tumor cell invasion via activation of the hypoxia-inducible factor 1-alpha/matrix metalloproteinase 14 pathway." (PMID 36769263, 2023). "As such, NOX5 stimulation by anlotinib led to tumor cells apoptosis via mitochondrial signaling." (PMID 36358519, 2022). "Notably, we concluded that several stromal components, such as fibroblast and adipose tissues, were activated to CAFs and resultantly induced the malignant progression of NOX5‐positive tumor cells." (PMID 34459125, 2021). "Nevertheless, the functionality of NOX5 in mediating tumor/stroma crosstalk remains a huge puzzle." (PMID 34459125, 2021). "Thus, investigating the relationship between SASP, NOX5/ROS axis‐mediated tumor/stroma crosstalk, and chemotherapies will provide applicable evidence for tumor treatment." (PMID 34459125, 2021).